BRCA2 (BRCA2 DNA repair associated)
Diseases named in the same sentence as BRCA2 in open-access papers (continued):
Sharing a sentence is not in itself a finding about the gene and the disease.
Infertility (24 papers, 2010 to 2026). "BRCA2 deficiency can lead to a meiotic disorder in spermatocytes, leading to infertility and directly affecting spermatogenesis, leading to male azoospermia or oligospermia." (PMID 38846492, 2024). "Female infertility increases the likelihood of the presence of pathogenic variants in BRCA1 or BRCA2 sevenfold; similarly, infertile men are also prone to pathogenic variants in BRCA1 or BRCA2." (PMID 39257928, 2024). "The Brca2-deficient mouse model driven by Gdf9-Cre is infertile, demonstrating that Brca2, a core gene in DNA repair and homologous recombination, is required for follicle and ovary development." (PMID 35855343, 2022). "BRCA2 mutations in mice and zebra fish led to infertility by inhibiting gamete development and inducing gamete death." (PMID 35804459, 2022). "Collectively, our data demonstrate that the defective follicular development, especially the compromised growth of activated follicles accounts for the infertility of Brca2-deficient female mice." (PMID 31209201, 2019). "To explore the reason leading to the infertility, we observed the morphology of ovaries from control and Brca2-deficient female mice." (PMID 31209201, 2019). "Some studies suggested that BRCA1 or BRCA2 mutations were involved in infertility or POI." (PMID 37325546, 2023). "Loss of BRCA2 function leads to infertility in all organisms studied." (PMID 34440403, 2021). "For example, by understanding the mechanisms utilized by mutations in the BRCA1 and BRCA2 to increase reproductive fitness, we may be able to further our understanding of the reproductive system and potentially discover novel treatments for infertility." (PMID 38952711, 2024). "Collectively, our data suggests that while the Shu complex and the BRCA2 C terminus have overlapping biochemical roles during meiotic HR, the Shu complex is more critical given the infertility of Shu mutant mice." (PMID 30305635, 2018). "In this study, our data reveals that mutations in rice BRCA2 lead to severe meiotic defects and infertility, but have no obvious effects on normal vegetative growth, unless exposed to genotoxic agent MMC." (PMID 33304374, 2020). "However, only few women with a pathogenic variant in BRCA1 or BRCA2 experience POI, as variants in BRCA1 and BRCA2 are not a monogenic cause of infertility." (PMID 39257928, 2024). "The BRCA2-MEILB2-BRME1 complex is required for the assembly of RAD51 and DMC1 at meiotic DSBs during spermatogenesis since deletion of any component in the complex diminishes RAD51 and DMC1 foci formation at recombination sites, causing impaired DSB repair and infertility." (PMID 34440403, 2021). "Other risk factors include: increased age, use of high-dose estrogens without progesterone for a long period, uninterrupted ovulation due to infertility, no pregnancies, no use of birth control, and defects in the BRCA1 or BRCA2 genes." (PMID 21827672, 2011).
Li-Fraumeni syndrome (21 papers, 2016 to 2026).
lung adenocarcinoma (21 papers, 2016 to 2026). A carcinoma that arises from the lung and is characterized by the presence of malignant glandular epithelial cells. "This case involves a 61-year-old male patient with a past history of Hodgkin’s Lymphoma and a heavy smoking history who developed lung adenocarcinoma and was found to have a BRCA2 mutation." (PMID 40162152, 2025). "According to The Cancer Genome Atlas database, BRCA1 and BRCA2 variants were observed in 3.0% and 4.8% of lung adenocarcinoma patients, respectively." (PMID 40182045, 2025). "One patient with lung adenocarcinoma and pathogenic germline BRCA2 mutation had biallelic gene inactivation due to the loss of heterozygosity, but did not receive platinum-based therapy." (PMID 36964191, 2023). "We did not observe an association between hormone receptor status with BRCA1, BRCA2 or EGFR mutation status in lung adenocarcinoma patients." (PMID 37461096, 2023). "In previous studies, most of the genes with germline mutations in lung adenocarcinoma were typical oncogenes and proto-oncogenes, which included BRCA2, CHECK2, CDKN2, BAP1, EGFR." (PMID 35712480, 2022). "Here, we present the case of a patient with lung adenocarcinoma harboring EGFR and somatic BRCA2 mutations, who developed resistance to third-generation EGFR tyrosine kinase inhibitors (TKIs) and subsequently exhibited durable response to Olaparib." (PMID 40182045, 2025). "In conclusion, we report a refractory lung adenocarcinoma patient with extensive leptomeningeal metastases, harboring EGFR and somatic BRCA2 co-mutations, who exhibited a lasting response to Olaparib despite resistance to third-generation EGFR-TKIs." (PMID 40182045, 2025). "Although lung cancer is not typically associated with BRCA mutations, 1% of lung adenocarcinomas can harbor such alterations, with BRCA2 being the predominant subtype." (PMID 40162152, 2025). "Interestingly, the expression of BRCA1, BRCA2, BLM and RAD51 was significantly associated with poor prognosis in lung adenocarcinoma." (PMID 37298484, 2023). "To determine whether BRCA2 inhibition could overcome innate olaparib resistance, we tested control or BRCA2 ASO treatment with olaparib in A549 lung adenocarcinoma and H2052 and 211H mesothelioma cell lines, all BRCA2-proficient." (PMID 26959114, 2016). "Here, we report a novel case of a middle-aged non-smoking female diagnosed with BRAF V600E and BRCA2 germline mutated lung adenocarcinoma, who had previously undergone a diverse array of cancer-targeted therapies, including PARP inhibitor, before the identification of the BRAF V600E mutation." (PMID 38715777, 2024). "However, another study that compared the rate of prevalence of BRCA1 and BRCA2 PGVs in patients with lung adenocarcinoma with ATM PGVs reported a higher prevalence of BRCA1 and BRCA2 PGVs." (PMID 38539485, 2024). "In multiple other tumor types (BRCA-breast, OV-ovarian, LIHC-liver hepatocellular carcinoma, LUAD-lung adenocarcinoma) there is a diversity of single copy deletions that ultimately coalesce over the genetic region around the RB1 locus, but not BRCA2 which is located on the same chromosome arm." (PMID 32242058, 2020).
glioblastoma (20 papers, 2011 to 2026). The most malignant astrocytic tumor (WHO grade IV). "In glioblastoma, loss of BRCA2, LIG4, or XRCC4 was associated with more frequent occurrence of complex genome rearrangements." (PMID 30420702, 2018). "Downregulation of HR (BRCA2 or RAD51) resulted in glioblastoma cell sensitization to TMZ and ACNU, which was ameliorated in the presence of the PARP inhibitor olaparib." (PMID 38068493, 2023). "It was shown that the siRNA for FANCD1/BRCA2 gene down-regulated and increased the sensitivity of glioblastoma A172 cells to both ACNU and TMZ." (PMID 21573016, 2011). "In contrast, four patients had progressive disease (PD); two patients with glioblastoma harboring BRCA1 c.5153-1G > C and BRCA2 p.S1982fs received a PARP inhibitor (veliparib and olaparib) and had PD after 1.4 and 0.2 months, respectively." (PMID 38143440, 2023). "In addition, it was found that FANCD1/BRCA2 small interference RNA efficiently enhanced cellular sensitivity toward ACNU and TMZ in human glioblastoma A172 cells." (PMID 21573016, 2011).
bladder cancer (19 papers, 2017 to 2026). "Patients with BRCA2 mutations tend to be more sensitive to chemotherapy and radiotherapy, leading to better prognoses in certain cancers, such as breast, ovarian, and bladder cancers." (PMID 39073402, 2024). "Of the bladder cancer patients enrolled in the study, fifty four (5.2%) carried a BRCA2 mutation (C5972T) (OR = 0.9; 95% CI 0.66–1.26; p = 0.6) A C5972T mutation was seen in the 36 affected men (4.7%) and in 18 women (6.7%)." (PMID 35395863, 2022). "The mutation C5972T in BRCA2 was observed in 54 bladder cancer patients (5.2%) and in 159 of 2791 healthy controls (5.7%) (OR = 0.9; 95% CI 0.66–1.26; p = 0.6)." (PMID 35395863, 2022). "Results from Sanger sequencing indicate that his healthy brother shares the same germline mutation of BRCA2 (c.1799_1804del, p.Tyr600_Gly602delinsTer), and his father died of bladder cancer at the age of 60." (PMID 35734583, 2022). "This was evidenced by delayed detection of the BRCA2 c.7934delG variant (initially in tumor DNA using NGS) in one of our study participants diagnosed with metachronous bladder cancer four years after receiving a low-risk MammaPrint result." (PMID 34660253, 2021). "Our machine learning approach re-classified several samples exhibiting genomic features inconsistent with original labels, identified a metastatic bladder cancer sample with a homozygous BRCA2 copy loss, and outperformed an existing exome-based classifier for BRCA2 deficiency." (PMID 36914848, 2023). "Finally, a further study performed on a Chinese population of 6064 patients and 8661 controls showed that BRCA2 p.Lys3326* plays an important role in the genetic susceptibility to urinary tract cancers since it is apparently associated with increased risk of bladder cancer." (PMID 29346284, 2018). "Co‐occurring BRCA2 alterations were identified in two patients (5.1%), one with gastrointestinal tumors and one with bladder cancer." (PMID 34898046, 2022). "Of the missense variants examined in fishing cat gene orthologs for human bladder cancer risk genes, DNA damage repair pathway genes BRCA1/2, CHEK2, and ATM all showed higher missense variant prevalence in the cohort; however, only BRCA2 showed a skewed distribution in TCC over healthy cats." (PMID 38580653, 2024). "However, the BRCA2-levels dropped substantially in both cell lines when hyperthermia was applied, implying that hyperthermia indeed affects HR in these two bladder cancer cell lines." (PMID 30550547, 2018). "Based on our data, we conclude that MIR4435-2HG exerts versatile functions in bladder cancer by transcriptionally regulating the expression of multiple cell-cycle regulators such as CCND1 and BRCA2." (PMID 37355516, 2023). "We found that BRCA2 and RAD51 were significantly upregulated in bladder cancer samples in the TCGA/BLCA RNA-Seq data, and that the expression of BRCA2 significantly correlated with that of RAD51 (Spearman R = 0.63; and p-value < 0.001)." (PMID 37355516, 2023). "Moreover, we found that MIR4435-2HG exerted versatile effects on bladder cancer,i.e., MIR4435-2HG promoted tumor cell proliferation and regulated the expression of multiple cell cycle regulators, such as CCND1 and BRCA2." (PMID 37355516, 2023). "Indeed, striking ER-stress in tumor may explain upregulation of BRCA2 and RAD51 expression in bladder cancer cells." (PMID 37355516, 2023). "All the examined bladder cancer cell lines were BRCA1 and BRCA2 wild-type, and therefore the observed viability is not influenced by BRCA mutational status." (PMID 40025053, 2025).
prostate tumors (19 papers, 2010 to 2025). "BRCA2- or ATM-deficient prostate tumors exhibit heightened sensitivity to PARP inhibitors via synthetic lethality." (PMID 40427518, 2025). "Next-generation sequencing (NGS) of the original prostate tumor biopsy identified the presence of a somatic BRCA2 mutation, the patient’s germline PMS2 mutation, and 13.1 mutations/Mb tumor mutational burden (TMB)." (PMID 38879699, 2024). "Our research reveals the survival adaptation mechanism of BRCA2-deficient prostate tumor cells and provides different angles for exploring synthetic lethal inhibitors in addition to targeting DNA damage repair pathways." (PMID 37934606, 2024). "Our previous report had also revealed that patient D had loss-of-heterozygosity of BRCA2 in his prostate tumors." (PMID 35734583, 2022). "Unlike for the other cancer types included, the proportion of prostate tumours with germline and somatic BRCA2 mutations was similar and approximately half of the BRCA2 alterations identified through tumour profiling are already present in the germline." (PMID 33106584, 2021). "BRCA1 and BRCA2 both are prostate tumor suppressors and their loss is associated with enhanced cell proliferation and overall cancer progression 34,35." (PMID 26311046, 2015). "Because of the lethality associated with AURKB defects, our focus was solely on investigating NSFL1C, and our findings revealed that its loss could promote the growth of prostate tumors with BRCA2 deficiency." (PMID 37934606, 2024). "Mutations in BRCA2 are observed in 13.3% of primary prostate tumors." (PMID 37170264, 2023). "The Cancer Genome Atlas (TCGA) analysis of 333 primary prostate tumors revealed BRCA2 and BRCA1 mutation rates that were quite similar to our study (3% and 1%, respectively), while ATM mutations were slightly more frequent than in our study (4% in TCGA vs. 1% in our study)." (PMID 38256334, 2023). "Identification of tumor genomic aberrations in BRCA2d prostate tumors may provide insight into the mechanisms of BRCA2-associated prostate carcinogenesis and progression, which could have downstream implications for prevention or therapeutics." (PMID 35715489, 2022). "We examined whether BRCA2-deficient (BRCA2d) prostate tumors have distinct genomic alterations compared with BRCA2-intact (BRCA2i) tumors." (PMID 35715489, 2022). "Prostate tumors that are BRCA2-deficient (BRCA2d) have aggressive genomic profiles that may contribute to the worse outcomes observed in this subset." (PMID 35715489, 2022). "This subset may be dependent on additional genetic modifiers or environmental factors that influence the risk of individuals carrying a BRCA2 mutation forming prostate tumours." (PMID 20585617, 2010). "While BRCA2- and ATM-mutated prostate tumors often exhibit more pronounced susceptibility to PARP blockade, some cases without BRCA mutations also display partial responses." (PMID 40427518, 2025). "CNA in prostate tumors among carriers of BRCA2 PSV have been reported to be 3-fold higher than in tumors without BRCA2 PSV, with copy number gains being more common in the region encompassing c-MYC13." (PMID 35715489, 2022). "Distinct tumor PSV, methylation, and expression patterns have been identified in BRCA2 compared with non-BRCA2 mutant prostate tumors." (PMID 34575947, 2021). "We also found that somatic mutations in BRCA2, NEIL3, ATM, and ATR were associated with higher mutational burden in prostate tumors." (PMID 32300177, 2020). "RAD51 displayed a higher incidence of LOH than BRCA2, which is considered a prostate tumor suppressor." (PMID 26433958, 2015). "This demonstrates not only that Brca2 can play a role in the initiation of prostate neoplasia but also that other factors are required for prostate tumour progression." (PMID 20585617, 2010). "This indicates that the influence of PP2A on prostate tumor growth might be contingent on the status of BRCA2." (PMID 37934606, 2024).
prostate tumors (continued). "In addition, AZD.0530 attenuated Src kinase activity and augmented PARP inhibitor‐mediated synthetic lethality in BRCA2‐altered prostate tumors." (PMID 38090653, 2022). "Hence, chromosomal region 15q14-21.1 was found to display a higher incidence of LOH than BRCA loci, especially BRCA2, which is considered a prostate tumor suppressor." (PMID 26433958, 2015).
fallopian tube cancer (18 papers, 2015 to 2025). A primary or metastatic malignant neoplasm that affects the fallopian tube. "The majority of BRCA mutations are located in the BRCA1 gene and the BRCA2 gene mutations comprise fewer cases and the latter also demonstrates a smaller risk for early fallopian tube carcinomas." (PMID 35147976, 2022). "In the series of 33 peritoneal/fallopian tube cancers analyzed, we identified only one patient (3.0%) carrying the BRCA2 c.156_157insAlu mutation (estimated total contribution of BRCA2 mutations of 5.5%) and no carriers of the BRCA1 c.3331_3334del mutation." (PMID 27532258, 2016). "Patients with BRCA1 or BRCA2 pathogenic variants should consider risk-reducing bilateral salpingo-oophorectomy after child-bearing or between the ages of 35–40 years to reduce ovarian and fallopian tube cancer risk." (PMID 31342359, 2019). "Approximately 30% of women with fallopian tube cancer have a mutation in BRCA1 or BRCA2." (PMID 26090245, 2015). "Whereas our estimation of the contribution of BRCA2 germline mutations for peritoneal/fallopian tube cancers in hospital-based cohorts is likely to be reliable, the evaluation of the contribution of BRCA1 mutations may require additional larger studies that include full gene analysis." (PMID 27532258, 2016). "The ML analysis identified CA125 levels, patient age, and MatoRRSO as primary risk factors for ovarian and fallopian tube cancers in BRCA1 and BRCA2 mutation carriers, consistent with current clinical understanding." (PMID 40303993, 2025). "Preventive strategies for tubal cancer, particularly for women at high risk due to genetic predispositions such as BRCA1 or BRCA2 mutations, often focus on risk-reducing salpingo-oophorectomy (RRSO)." (PMID 39274288, 2024). "With respect to BRCA2, 61.1% of female PV carriers had BC (mean age at diagnosis: 43.6, range 21–90), 10.1% had OC or fallopian tube cancer (mean age at diagnosis: 57.9, range 31–99) and 32.9% were free of these cancers (mean age at inclusion: 42.1, range 19–91)." (PMID 30430080, 2018). "Another study performed on 108 patients with fallopian tube cancer identified 21% of patients with a mutation in BRCA1 and 9% in BRCA2, whereas one study performed on 79 patients with peritoneal/fallopian tube cancer identified mutations in BRCA1/BRCA2 in 23% of the patients." (PMID 27532258, 2016). "In the 33 patients with peritoneal/fallopian tube cancer analyzed, none was carrier of the BRCA1 c.3331_3334del mutation and one patient (3.0%) was a carrier of the BRCA2 c.156_157insAlu mutation." (PMID 27532258, 2016). "In 2018, the SOLO-1 trial randomized 391 patients with BRCA1 and/or BRCA2 mutation, FIGO Stage III or IV high-grade serous or endometrioid ovarian/primary peritoneal/fallopian tube cancer, regardless of surgical outcome and/or complete/partial response after first-line platinum-based chemotherapy." (PMID 38931448, 2024).